REP15 (RAB15 effector protein)
Description:
Effector that interacts with Rab GTPases in their active form (GTP-bound) including RAB15, RAB3A-D and RAB34. Controls downstream signaling such as cell proliferation and cell migration. Also regulates transferrin receptor recycling from the endocytic recycling compartment.
Synonyms: RAB15EP
Tractability: Small molecule: a structure with a bound ligand is known.
Gene: Protein-coding gene on chromosome 12 (27,696,447 to 27,697,596, forward strand). Ensembl gene ENSG00000174236.
Subcellular location: Early endosome membrane
Gene Ontology:
Molecular function: protein binding
Biological process: receptor recycling; transferrin transport
Cellular component: early endosome membrane; endosome membrane; perinuclear region of cytoplasm; recycling endosome
Genetic constraint (gnomAD): Loss-of-function variants: 4 observed, 3.64 expected, observed/expected ratio (o/e) 1.1, 90% interval 0.51 to 1.87. That is too few expected variants to judge how well the gene tolerates losing a copy. Missense variants: 242 observed, 282.26 expected, observed/expected ratio (o/e) 0.86, 90% interval 0.77 to 0.95. Synonymous variants: 98 observed, 102.9 expected, observed/expected ratio (o/e) 0.95, 90% interval 0.81 to 1.13.
Homologues: Orthologues: chimpanzee REP15 (99% identical), macaque REP15 (95% identical), dog REP15 (85% identical), pig MRPS35 (76% identical), rabbit REP15 (74% identical), mouse Rep15 (73% identical), rat Rep15 (73% identical), tropical clawed frog rep15 (47% identical).
Diseases named in the same sentence as REP15 in open-access papers:
REP15 is named in the same sentence as 6 diseases in open-access papers, as found by Europe PMC text mining. Sharing a sentence is not in itself a finding about the gene and the disease. The quoted sentences say what the papers report.
glioblastoma (1 paper, 2022). The most malignant astrocytic tumor (WHO grade IV). "Rep15 depletion in U138MG glioblastoma cells impairs cell proliferation, cell migration and receptor recycling, underscoring the need for further clarification of the role of Rep15 in cancer." (PMID 35871249, 2022). "Here, the authors show that Rep15 also interacts with Rab3 paralogs and Rab34, present crystal structures of Rep15:Rab complexes and find that Rep15 depletion in glioblastoma cells decreases proliferation and mobility." (PMID 35871249, 2022). "Rep15 knockout experiments in U138MG glioblastoma cells show that Rep15 depletion leads to a decrease in cell proliferation and cell migration and also influences transferrin recycling." (PMID 35871249, 2022).
neurodevelopmental disorder (2 papers, 2023). A behavioral and cognitive disorder with onset during the developmental period that involves impaired or aberrant development of intellectual, motor, or social functions. "The results identified one potential KS candidate gene (TSPAN11), seven candidate genes for the neurodevelopmental disorder (TM7SF3, STK38L, ARNTL2, ERGIC2, TMTC1, DENND5B, and ETFBKMT), and four candidate genes for KS with ID (INTS13, REP15, PPFIBP1, and FAR2)." (PMID 37034680, 2023). "As a result, we identified a dozen candidate genes: TSPAN11 as a potential KS candidate gene, TM7SF3, STK38L, ARNTL2, ERGIC2, TMTC1, DENND5B, and ETFBKMT as candidate genes for the neurodevelopmental disorder, and INTS13, REP15, PPFIBP1, and FAR2 as candidate genes for KS with ID." (PMID 37563198, 2023).
REP15 also shares sentences with these, for which no sentence is quoted: cancer (1 paper); colorectal cancer (1); rectum adenocarcinoma (1); tumor (1).